LMO2 (LIM domain only 2)
Diseases named in the same sentence as LMO2 in open-access papers (continued):
Sharing a sentence is not in itself a finding about the gene and the disease.
leukemia (continued). "Interestingly, previous studies have shown that the enhancer/promoter loop interactions required looping factor LDB1 and TAL1/GATA/LMO2 transcription super complexes that are present in both normal hematopoiesis and T-ALL leukemia." (PMID 32086528, 2020). "Unlike its role in leukemias, LMO2 expression in DLBCL is not correlated with any somatic genetic alterations, but with the germline genetic variation." (PMID 26869285, 2016). "We also provide additional evidence supporting the notion that IL2RG and LMO2 cooperate in leukemia induction but are not sufficient and require additional cooperating mutations." (PMID 19461887, 2009). "Consistent with this, patient #4, who developed leukemia in the French trial, and patient #8, who developed leukemia in the English trial, showed rearrangement of the SIL-TAL1 loci along with insertional activation of LMO2." (PMID 19461887, 2009). "LMO2 plays an important role in hematopoiesis and leukemogenesis, Begay-Muller’s research indicated that AF6, a recurrent fusion partner of MLL, bound to LMO2 and may be involved in mixed lineage leukemia (Begay-Muller, Ansieau & Leutz, 2002)." (PMID 31523525, 2019). "However, recent work showed that deletion of Prh/HHEX does not always block Lmo2-induced leukemia indicating that these proteins can act via parallel pathways." (PMID 26877867, 2016). "There may be a risk involving the oncogenic potential of LMO2 in reprogrammed cells, particularly given the appearance of leukaemias in the X-SCID trials following retroviral insertional activation of LMO2 and the evidence of neoplasia in models of enforced lmo2 expression." (PMID 26108219, 2015). "Interestingly, deletion of PRH in the thymus of Lmo2 transgenic mice did result in a reduction in the transplantation capacity and the radioresistance of Lmo2-transgenic thymocytes but did not inhibit the development of the leukaemia." (PMID 26877867, 2016). "Targeted and restricted Lmo2 expression in mouse HSCs, by placing LMO2–TdTomato cDNA under the control of the stem-cell-specific Sca1 promoter, resulted in a highly disseminated human-like T acute lymphoblastic leukaemia (T-ALL), with the resulting leukaemia cells lacking expression of Lmo2." (PMID 32213936, 2020).
T-cell acute lymphoblastic leukemia (25 papers, 2006 to 2025). Acute lymphoblastic leukemia of T-cell origin. "The basic helix-loop-helix proteins TAL1, LYL1 and the LIM-only protein LMO2 were identified from the breakpoints of chromosomal translocations associated with T cell acute leukemia." (PMID 35508511, 2022). "Ectopic expression in T-cell precursors of LIM only protein 2 (LMO2), a key factor in hematopoietic development, has been linked to the onset of T-cell acute lymphoblastic leukaemia (T-ALL)." (PMID 32477463, 2020). "LIM only 2 (LMO2) was originally identified through its homology to LMO1 and was shown to cause T-cell acute lymphoblastic leukaemia, as a consequence of chromosomal translocations involving LMO2 and the T-cell receptor genes." (PMID 28973433, 2017). "Accumulating evidence suggests that LMO1 and LMO2 act as oncogenic proteins in T-cell acute lymphoblastic leukemia, whereas LMO4 has recently been implicated in the genesis of breast cancer." (PMID 16420690, 2006). "Loss of LMO2 protein inhibits T cell acute leukaemia (T-ALL) cell growth." (PMID 41385269, 2025). "Another top hub gene LMO2 transcription start site is located approximately 25 kb downstream from the 11p13 T-cell translocation cluster (11p13 etc.), where a number of T-cell acute lymphoblastic leukemia-specific translocations occur." (PMID 35893690, 2022). "For example, in the proto-oncogene LMO2-induced T-cell acute lymphoblastic leukemia, LMO2 along with LDB1, b-HLH and GATA formed a multi-subunit transcription complex, which was required for the oncogenic transformation of immature thymocytes." (PMID 35071313, 2021). "The LIM domain Only protein – 2 (LMO2) was first discovered as the recurrent chromosomal translocation partner of a TCR locus in a subset of patients with T-cell acute lymphoblastic leukemia (T-ALL)." (PMID 33193725, 2020). "LMO1 and LMO2 are oncogenes that are recurrently translocated and overexpressed in T-cell acute lymphoblastic leukemia (T-ALL)." (PMID 32195177, 2020). "Chromosomal translocations between chromosomes 11 and 14, 11 and 13, and 7 and 11 activate the LMO2 gene, the product of which is a specific marker of T-cell ALL (T-ALL)." (PMID 31861691, 2019). "LMO1 and LMO2 expression is dysregulated by multiple mechanisms in T-cell acute lymphoblastic leukemia, LMO2 is overexpressed in prostate cancer, and LMO3 is upregulated in neuroblastoma." (PMID 27780223, 2016). "Aberrant expression of Lmo2 results in the development of T-cell related diseases; indeed Lmo2 is located at a recurrent site of T-cell acute lymphoblastic leukemia (T-ALL) specific translocation." (PMID 23285212, 2012). "It has been reported that BEX2 is a binding partner of LMO2, a T-cell oncogene with recurrent chromosomal translocations in T-cell acute leukemias, and enhances the transcriptional activity of LMO2-NSCL2 complex." (PMID 20482821, 2010). "LIM domain only 2 (LMO2) was first identified in T-cell acute lymphoblastic leukemia (T-ALL)." (PMID 27028859, 2016). "Likewise, FOXP3 downregulation attenuated the expression of LIM Domain Only 2 (LMO2) but increased the expression of an oncogenic transcription factor T-cell acute lymphocytic leukemia protein 1 (TAL1) at mRNA level in T-cell acute lymphoblastic leukemia (T-ALL) cells." (PMID 31815635, 2019). "LMO1, LMO2 and LMO3 express specificity in different cells of the adult mammalian central nervous system, and LMO1 and LMO2 act as oncogenes in acute T-cell lymphoblastic leukemia." (PMID 25829251, 2015). "In T-cell ALL, up to 22 different oncogenes have been identified as TCR translocation partners; the LMO2, TAL1, and TLX1 genes were most frequently involved in these rearrangements and the majority of all TCR translocations involved the TRD locus." (PMID 25515027, 2014).
T-cell acute lymphoblastic leukemia (continued). "In erythroid differentiation, core transcriptional networks play crucial roles, which include gata binding protein 1 (GATA1), T-cell acute lymphoblastic leukemia/stem cell leukemia (TAL1/SCL), Krüppel-Like Factor 1 (KLF1), LIM domain only 2 (LMO2), and LIM domain binding protein 1 (LDB1)." (PMID 37296674, 2023). "Analyses of leukemic cell clones from these patients revealed that the murine leukemia virus (MLV) vector had integrated proximal to the promoter of an oncogene involved in T-cell acute lymphoblastic leukemia, LIM-only protein 2 (LMO2), resulting in aberrant expression." (PMID 19725963, 2009).
acute lymphoblastic leukemia (18 papers, 2010 to 2025). Leukemia with an acute onset, characterized by the presence of lymphoblasts in the bone marrow and the peripheral blood. "The LMO2 (LIM domain only 2) gene encodes a cysteine-rich, two protein structural domain that plays an important role in hematopoietic development; moreover, its ectopic expression in T cells leads to the onset of acute lymphoblastic leukaemia (ALL)." (PMID 24466173, 2014). "LMO2 is an oncogene that is overexpressed in T-cell acute lymphoblastic leukemia (T-ALL) due to chromosomal translocation into the vicinity of the T-cell receptor locus." (PMID 31819055, 2019). "Recent work has shown that elevated Prh/HHEX expression occurs in Early T cell progenitor acute lymphoblastic leukaemia (ETP-ALL) and that this gene is a direct target of the LMO2 oncoprotein." (PMID 26877867, 2016).
T-cell leukemia (11 papers, 2009 to 2024). A malignant disease of the T-lymphocytes in the bone marrow, thymus, and/or blood. "The nuclear adapter Ldb1 is required for Lmo2 oncogene-induced thymocyte self-renewal and T-cell leukemia in a mouse model of T-ALL." (PMID 37573405, 2023). "PRH can phenocopy the Lmo2 oncoprotein in inducing self-renewal when overexpressed in mice and elevated PRH causes a T-cell leukemia, which is strikingly similar to that caused by Lmo2." (PMID 26877867, 2016). "The LMO2 oncogene is deregulated in the majority of human T-cell leukemia cases and in most gene therapy-induced T-cell leukemias." (PMID 24465765, 2014). "Moreover, transgenic overexpression of Lmo2 in various murine tissues only results in T-cell leukemia, indicating its involvement exclusively in T-cell malignancies when abnormally expressed." (PMID 34382935, 2021). "Moreover Lmo2-transgenic mice with conditional deletion of Prh/HHEX showed a significantly delayed onset of the T-cell leukemia." (PMID 26877867, 2016). "Experimental data showed that LMO2 and LYL1 co-expression is frequent in ETP-ALL, and is critical for the LMO2-dependent upregulation of a stem cell-like gene signature, aberrant self-renewal of thymocytes and consequent generation of T-cell leukemia." (PMID 34930475, 2021).
lymphoma (10 papers, 2009 to 2024). A malignant (clonal) proliferation of B- lymphocytes or T- lymphocytes which involves the lymph nodes, bone marrow and/or extranodal sites. "In the lymphatic and hematopoietic system, in addition to expression in the normal lymphoid germinal center, LMO2 is expressed in germinal center-derived lymphomas, acute B-lymphoblastic leukemia, and acute myeloid leukemia (AML)." (PMID 31484540, 2019). "We found that all tumors expressed high levels of Pu.1 and Lmo2 relative to lymphoma-free splenocytes from age-matched tumor-free mice with the same genotype." (PMID 27588406, 2016). "Down-regulation of miR-223 also has been demonstrated in hepatocellular carcinoma, acute myeloid leukemia and chronic lymphocytic leukemia, and shown to regulate the important hematopoietic regulator LMO2 that is commonly expressed in lymphoma." (PMID 21592325, 2011). "FISH analyses using BAC clones covering lymphoma breakpoints (BCL2, BCL6, BCL11A, CCND1, CCND3, IG-H/K/L, JAK2, LMO2, MYC, PAX5, REL) all tested normal, excluding rearrangements at these loci." (PMID 26599546, 2015).
breast cancer (9 papers, 2005 to 2021). A primary or metastatic malignant neoplasm involving the breast. "Correspondingly, LMO2 was associated with rather different cellular functions and signal pathways in different breast cancer subtypes, as well as between normal and malignant breast tissues." (PMID 29507663, 2018). "The lmo2 gene was traditionally recognized as a proto-oncogene in hematopoietic system but its functions in breast cancers remained largely unclear." (PMID 29507663, 2018). "Herein we found that even in a certain cancer type, such as breast cancer, LMO2 functioned diversely in a subtype-dependent manner." (PMID 27880729, 2017). "Immuno-blots of cytosolic and nuclear fractions from MDA-MB-231 and MCF-7 breast cancer cells revealed that LMO2 protein was much more abundant in the cytoplasm than in the nucleus." (PMID 27880729, 2017). "In the wound-healing assay, overexpression of LMO2 increased, while knocking-down of LMO2 decreased, cell migration in basal-type breast cancer cell lines MDA-MB-231 and SUM159." (PMID 27880729, 2017). "Mouse mammary cancer cells with intact Jak2 (Jak2+/+) resulted in up regulation of Lmo2 and Nanog in MUC16-Cter dependent manner and this dependence was abrogated in cells genetically deleted for Jak2 (Jak2−/−)." (PMID 25691062, 2015). "Based on the Cancer Genome Atlas (TCGA) breast cancer dataset, herein we found that the significantly LMO2-correlated genes in normal or malignant samples were enriched in rather divergent cellular pathways, suggesting the function complexity of LMO2 in breast tissues." (PMID 29507663, 2018). "Additionally, potential LMO2 functions on other breast cancer subtypes were also investigated in the TCGA dataset and interestingly, high LMO2 expression was found to predict a shorter overall survival in luminal A-type whereas a better outcome in Her2-type." (PMID 27880729, 2017). "Although LMO2 is traditionally recognized as a transcriptional factor, our data indicated a primarily cytoplasmic location of LMO2 in normal breast duct epithelia and breast cancer cells." (PMID 27880729, 2017). "Mechanistically, we demonstrated that MUC16-Cter results in nuclear translocation of JAK2, which preferentially phosphorylates histone-3 and up regulates stemness-specific genes such as LMO2 and NANOG, which was further validated using Jak2 deficient (Jak2−/−) mouse mammary tumor cells." (PMID 25691062, 2015). "LMO1 and LMO2 overexpression is linked to T-cell tumourigenesis and LMO4 has been associated with breast oncogenesis, where overexpression is observed in approximately 50% of breast cancer cell lines and primary breast cancers." (PMID 16280053, 2005). "Instead of directing flows with cell cycle regulators as in the case of breast cancer, there are in general uncoordinated functions between RB1 with transcriptional regulators LMO2 and PML and RFC1 that regulate DNA replication." (PMID 26975659, 2016).
prostate carcinoma (6 papers, 2016 to 2023). A carcinoma that arises from epithelial cells of the prostate gland. "LIM domain only 2 (LMO2) was put forward as a new marker in prostate cancer, which increases the viability of prostate cancer cells via releasing FGF-9 and IL-11 from prostate fibroblasts." (PMID 36865499, 2023). "The top 10 genes upregulated in TRAMP mice are TNFSF, RPL22, EIF4, SLC2A, LMO2/3, KRT, RPS21, RPS19, RPL21, and NEK of which all 10 were upregulated in human prostate cancer dataset." (PMID 30972102, 2019). "A recent study has also shown that the LIM domain only 2 (LMO2, a key regulator of hematopoietic stem cell development) is transcriptionally repressed by AR in prostate fibroblasts and that LMO2 is elevated in primary human prostate cancer vimentin+/αSMA+ CAFs in response to enzalutamide treatment." (PMID 36671452, 2022).
chronic myeloid leukemia (5 papers, 2015 to 2023). "The hallmark BCR-ABL fusion in chronic myeloid leukemia (CML) and high expression of LMO2 in DLBCL both lead to BRCAness or HR deficient (HRD) phenotype." (PMID 37306526, 2023). "Some oncogenes influence the fate of stem cells: LMO2, BCR-ABLp190, and BCR-ABLp210 are specifically associated with and drive human T acute lymphoblastic, B acute lymphoblastic leukemia, and chronic myeloid leukemia (CML), respectively." (PMID 33807298, 2021). "However, TG101209 resulted in significant down regulation of LMO2 in K562 chronic myelogenous leukemia cell line." (PMID 25691062, 2015). "The BCR-ABLp190, LMO2, and BCR-ABLp210 oncogenes play a role in human B-lymphocyte, acute T-lymphoblastic, and chronic myeloid leukaemia, respectively." (PMID 31861691, 2019).
acute myeloid leukemia (4 papers, 2011 to 2024). Acute myeloid leukemia (AML) is a group of neoplasms arising from precursor cells committed to the myeloid cell-line differentiation. "In LYL1/LMO2 only few rearrangements were found, underlying the stem cell character of LYL1/LMO2 with similarities to acute myeloid leukemia (AML)." (PMID 38744920, 2024). "LMO2 was also expressed in myeloid and erythroid progenitor cells, megakaryocytes, lymphocytes, and acute myeloid leukemia." (PMID 31484540, 2019). "Analysis of gene expression profiling data from large cohorts of acute myeloid leukaemia (AML) patients confirmed that LMO2 expressed at a markedly lower level in APL patients in comparison to non‐APL AML patients." (PMID 30320491, 2018).
Burkitt lymphoma (4 papers, 2019 to 2024). A rare form of malignant mature B-cell non-Hodgkin lymphoma. "Interestingly, LMO2 expression is observed in lymphomas derived from germinal center lymphocytes, including FL, Burkitt lymphoma (BL), and DLBCL, as well as in NLPHL." (PMID 38179383, 2023). "In our study, we found that LMO2 protein was 100% positively expressed in HGBL; however, it was only expressed in one of Seventy-five Burkitt lymphomas." (PMID 31484540, 2019). "It has a Burkitt-like immunophenotype (CD10+, BCL6+, BCL2−) but MYC expression is weak or negative, lacks MYC rearrangement, and is in contrast to Burkitt lymphoma 50% of the cases express LMO2." (PMID 37555980, 2023).
diffuse large B-cell lymphoma (4 papers, 2010 to 2025). "Moreover, LMO2 expression is associated with improved survival in Diffuse Large B-Cell Lymphoma (DLBCL), possibly due to its inhibitory effect on HRR activity in DLBCLs, thus providing a rationale for the therapeutic use of PARPi in LMO2-positive DLBCLs25." (PMID 40764600, 2025). "Gene expression profiling (GEP) identified LMO2 as one of the genes associated with the germinal center (GC) signature in secondary follicles and the GCB-like profile in diffuse large B-cell lymphomas (DLBCL)." (PMID 39001439, 2024). "LMO2, MYBL1, BCL6, LRMP, and CCND2 in our 35 signature genes were also reported in Lossos's 36 genes, which predicted survival in diffuse large-B-cell lymphoma." (PMID 20856936, 2010). "Finally, in B-cell lineage, and in Diffuse Large B-cell Lymphoma in particular, CBFA2T3 is reported to be part of the LMO2 complex regulating kinetochore function, chromosome assembly, and mitosis." (PMID 33743795, 2021).
pancreatic cancer (4 papers, 2015 to 2021). "LMO2 expression is considered a prognostic biomarker not only in hematological malignancies, but also in solid tumors as pancreatic cancer and lung cancer." (PMID 33591648, 2021). "Forced expression of a 17 kDa MUC16-Cter fragment in pancreatic cancer cells mediated nuclear translocation of JAK2 which preferentially phosphorylated tyrosine 41 of histone H3 (H3Y41) in a STAT-independent manner and up regulated stemness specific genes LMO2 and NANOG." (PMID 29682172, 2018).